LGALS7 (galectin 7)
Diseases named in the same sentence as LGALS7 in open-access papers (continued):
Sharing a sentence is not in itself a finding about the gene and the disease.
tumor (continued). "Take the uterus for examples, galectin-7 up-regulate MMP-9 expression, thereby promotes tumor progression and metastasis in cervical squamous carcinoma, while in normal uterus, it promotes uterine repair following menstruation." (PMID 27259255, 2016). "The nomogram illustrated that tumor size contributed largest to the prognostication (weighted ratio = 0.414), while necrosis, LVI as well as galectin-7 showed a minor impact on outcome (weight ratio = 0.079, 0.075, 0.071, respectively)." (PMID 27259255, 2016). "The increase in tumor malignancy and metastatic phenotype were attributed to the induction of MMP-9 expression by galectin-7." (PMID 23985992, 2013). "Galectin 7 injection suppressed MC38 tumor growth in WT mice but not in PD-1 KO mice or anti-mPD-1 antibody injected mice." (PMID 38503797, 2024). "Indeed, ectopic expression or addition of exogenous galectin-7 in the DLD-1 human colon carcinoma cell line and the neuroblastoma cells SK-N-MC, respectively, drastically reduced tumor cell proliferation." (PMID 29854732, 2018). "Further observations in human lymphoid diseases suggested correlations between tumour progression and accumulation of galectin-7 while no expression was detected in normal tissues." (PMID 29257082, 2017). "Results indicated that tumor size (P < 0.001), pathological T stage (P = 0.002), necrosis (P = 0.002), Fuhrman grade (P = 0.009), sarcomatoid (P = 0.010), LVI (P = 0.003) and galectin-7 (P = 0.003) were independently predictive factors of OS, while ECOG-PS (P = 0.280) showed no significance." (PMID 27259255, 2016). "The nomogram integrating tumor size, pathological T stage, necrosis, Fuhrman grade, sarcomatoid, LVI and galectin-7 expression shows a better prognostic accuracy in OS than the traditional models, thus has a better effectiveness in non-metastasis ccRCC patients OS prediction." (PMID 27259255, 2016). "In this study, we evaluated the galectin-7 expression in tumor tissues by immunohistochemistry and analyzed the relationship between galectin-7 expression and overall survival in 416 patients with non-metastasis ccRCC." (PMID 27259255, 2016). "Galectin-7 was absent in UC regions but strongly expressed in Ba/Sq-differentiated tumor nests." (PMID 41917522, 2026). "By deleting galectin-7, metastasis could be suppressed without affecting the growth of the primary tumor." (PMID 39465762, 2024). "In this case, galectin-7 expression could be induced by nuclear factor-kappa B, a transcription factor and a positive regulator of MMP-9 known to be expressed in highly aggressive tumor cells." (PMID 24515895, 2014). "The syngeneic mouse tumor models confirmed that galectin 7 reduces the percentage of CD4+ T cells in WT mice but not in PD-1 KO mice, suggesting a potential role of galectin 7 in PD-1." (PMID 38503797, 2024).
adenocarcinoma (2 papers, 2024 to 2025). A common cancer characterized by the presence of malignant glandular cells. "Galectin-7 expression in adenocarcinoma sorted by clinical features." (PMID 39465762, 2024).
bacterial infection (2 papers, 2020 to 2021). "GAS proliferation was increased following galectin-7 knockdown in HaCaT cells, which indicates that intracellular galectin-7 plays a critical role in intracellular immunity in the response against bacterial infection." (PMID 34827718, 2021). "Next, galectin-7 function during bacterial infection was investigated by performing infection assays on galectin-7-knockdown cells." (PMID 33425778, 2020). "Notably, GAS proliferation was increased following galectin-7 knockdown in HaCaT cells, which indicates that intracellular galectin-7 plays a critical role in intracellular immunity in the response against bacterial infection." (PMID 33425778, 2020).
infection (2 papers, 2014 to 2020). The state of being infected such as from the introduction of a foreign agent such as serum, vaccine, antigenic substance or organism. "To examine the infection efficiency and intracellular distribution of Ad-FLAG-GAL7, we performed immunofluorescence labeling for overexpressed galectin-7." (PMID 24515895, 2014).
LGALS7 also shares sentences with these, for which no sentence is quoted: gastric adenocarcinoma (2 papers); actinic keratosis (1); basal cell carcinoma (1); bladder squamous cell carcinoma (1); brain cancer (1); cardiovascular diseases (1); cerebral amyloid angiopathy (1); chronic obstructive pulmonary disease (1); diabetes (1); head and neck squamous cell carcinoma (1); leukemia (1); liver cancer (1); liver fibrosis (1); lung adenocarcinoma (1); Miscarriage (1); nevus (1); pancreatic cancer (1); small cell lung carcinoma (1); squamous cell carcinoma of the tongue (1); squamous cell tumor (1); systemic sclerosis (1); thyroid (1); urothelial cell carcinoma (1); uveal melanoma (1).